IL26 (interleukin 26)
Diseases named in the same sentence as IL26 in open-access papers (continued):
Sharing a sentence is not in itself a finding about the gene and the disease.
Crohn disease (17 papers, 2010 to 2024). A gastrointestinal disorder characterized by chronic inflammation involving all layers of the intestinal wall, noncaseating granulomas affecting the intestinal wall and regional lymph nodes, and transmural fibrosis. "The induction of IL-26 has been reported in many inflammatory diseases, including Crohn’s disease, chronic obstructive pulmonary disease, and sepsis." (PMID 34572149, 2021). "More specifically, in Crohn's disease, RORγt+ Th17 cells infiltrating inflamed mucosa secrete IL-26 which can, in turn, induce the secretion of inflammatory cytokines by epithelial cells." (PMID 30809226, 2019). "The levels of circulating IL-26 are elevated in patients with Crohn's disease and an increased expression of IL-26 mRNA is observed within inflammatory colonic lesions." (PMID 30809226, 2019). "Single nucleotide polymorphism in the IL26 gene results in reduced bacterial killing, elevated concentration of pro-inflammatory cytokines, and increased consumption of anti-TNF antibodies in Crohn’s disease patients with translocated bacterial DNA." (PMID 29967613, 2018). "Increased expression of the cytokine IL-26 has been reported in biopsies of Crohn’s disease and ulcerative colitis patients." (PMID 29967613, 2018). "The protein IL-26 has been evidenced in some Th17 cells infiltrating colonic lesions in patients with Crohn's disease." (PMID 23055831, 2012). "Supporting observations in the intestinal lesions in Crohn's disease patients, we observed that some infiltrating T cells, including Th17 cells, express IL-26 in RA joints." (PMID 23055831, 2012). "Furthermore, IL-26 mRNA levels in PBMCs were significantly lower in patients with complicated Crohn’s disease." (PMID 35463017, 2022). "In addition, FOSL factors downregulated IL-26 expression, a cytokine that marks inflammatory Th17-populations in patients suffering from Crohn's disease." (PMID 35511484, 2022). "Additionally, in intestinal epithelial cells from patients with Crohn’s disease, IL-26 activates STAT1/3, ERK1/2, stress-activated protein kinase/JNK1/2, and Akt phosphorylation, leading to increased expression of proinflammatory cytokines." (PMID 31831038, 2019). "Based on the original observation of an elevated expression of IL-26 in Crohn's disease, the authors reported that IL-26 induces the expression of the pro-inflammatory cytokines IL-8 and TNFα as well as the regulatory cytokine IL-10 in human gut epithelial cells." (PMID 30809226, 2019). "Interestingly, the translocation of bacterial DNA from the gut into the peripheral blood of Crohn’s disease patients leads to increased IL-26 concentrations." (PMID 29967613, 2018). "Even though an upregulation of IL-26 has been reported in Crohn's disease, a Th1- and Th17-mediated inflammatory disorder, the potential role of IL-26 in human disease remains partially unknown." (PMID 23055831, 2012). "IL-26 has been also reported overexpressed in Crohn's disease, suggesting that it may be involved in the physiopathology of chronic inflammatory disorders." (PMID 23055831, 2012). "In colonic biopsies of patients with inflammatory bowel disease (Crohn’s disease), the number of infiltrating IL-26 positive cells, presumably Th17 cells, was increased, IL-26 mRNA expression was upregulated and correlated with IL-8; IL-22 mRNA expression and IL-26 serum levels were increased." (PMID 23875025, 2013). "For patients with either Crohn’s disease or UC, Th17 cells are abundant in inflamed intestine terminal ileum and produce IL17A, IL17F, IL26 and IFNγ." (PMID 34390759, 2021).
asthma (14 papers, 2010 to 2025). "In patients with asthma, overexpression of IL-26 is associated with elevated expression of IL-17A, RAR-related orphan receptor C (RORC), IL-1β, IL-6, and tumor TNF, driven by activation of the IL-20R1/IL-10R2 receptor complex." (PMID 41516201, 2025). "Nevertheless, it is interesting that so many of the asthmatic subjects in our study had significantly elevated levels of IL-26 and/or IL-17 A, cytokines which are typically associated with more severe and often steroid-resistant asthma." (PMID 38622712, 2024). "The association of systemic IL-26 with improved asthma control is compatible with the cellular sources being recruited into the airways in severe asthma, which supports that this kinocidin bears potential as a biomarker and therapeutic target." (PMID 38622712, 2024). "A single nucleotide polymorphism (rs3741809) in the IL26 gene is associated with susceptibility to allergic rhinitis and the levels of IL-26 in sputum samples are positively correlated with pediatric asthma severity." (PMID 30809226, 2019). "Growing evidence suggests an association between IL-26 and asthma." (PMID 41516201, 2025). "Additionally, these investigators identified IL-26 single nucleotide polymorphisms (SNPs) associated with either increased or decreased risk of developing asthma." (PMID 38622712, 2024). "This may explain the lack of clinical efficacy with anti-IL-17 and IL-17 receptor approaches in severe asthma and that perhaps a broader approach is required to block additional Th17-associated cytokines such IL-22 and IL-26." (PMID 34022896, 2021). "In this pilot study, we examined associations between local interleukin (IL)-26, disease severity and biomarkers of Th2-mediated inflammation in a well-defined cohort of pediatric patients (14 years median age, 41 % females) with controlled (n = 28) or uncontrolled (n = 48) asthma." (PMID 27029915, 2016). "IL-26 has been proposed as a potential biomarker for asthma severity, particularly in patients with non-Th2-dominant inflammation." (PMID 41516201, 2025). "In children with uncontrolled asthma, the levels of IL-26 in induced sputum were higher than those in children with controlled disease." (PMID 41516201, 2025). "While there are differences in the populations assessed in these studies, the differences in local and systemic IL-26 concentrations in subjects with asthma suggest that are compartment-specific mechanisms regulating the production of IL-26." (PMID 38622712, 2024). "In our study material, we observed that, amongst children with asthma, increasing systemic IL-26 levels correlate with increasing ACT scores." (PMID 38622712, 2024). "Previous studies have reported that increasing local IL-26 concentrations correlate with worsening disease severity in adults with asthma." (PMID 38622712, 2024). "Taken together, these previous findings suggest that IL-26 expression is altered in patients with asthma and motivate further study, given the limited conceptual understanding of the role of IL-26 in asthma." (PMID 38622712, 2024). "The aim of the current study was to determine how systemic IL-26 concentrations relate to allergen sensitization, asthma severity, and to concentrations of the archetype Type 17 cytokine IL-17 A, in children." (PMID 38622712, 2024). "Specifically, we assessed the relationship between systemic IL-26 concentrations and two surrogate markers of asthma exacerbations, namely hospitalizations and systemic corticosteroid usage." (PMID 38622712, 2024). "Third, we show that the plasma concentration of IL-26 is higher in COVID-19 patients with comorbid obstructive lung disease (i.e., asthma and/or COPD), which agrees with previous studies on asthma." (PMID 39430762, 2024). "To this end, we compared systemic IL-26 to daily inhaled corticosteroid doses in the patients with asthma." (PMID 38622712, 2024). "Here, we determined how systemic IL-26 relates to allergen sensitization, asthma severity, and to IL-17 A in children." (PMID 38622712, 2024).
asthma (continued). "Previous studies show that local IL-26 concentrations in the airways are higher in patients with uncontrolled than in those with controlled asthma, and that this intriguing cytokine bears biomarker potential." (PMID 38622712, 2024). "Children with asthma had significantly higher levels of both IL-26 and IL-17 A than children in the control group." (PMID 38622712, 2024). "Previous studies have shown that the IL-26 secretion can be used as a biomarker for childhood asthma." (PMID 36313877, 2022). "Given that IL-26 is elevated systemically in dog allergen-sensitized children with asthma, we considered whether IL-26 may be a marker of disease severity in asthma." (PMID 38622712, 2024). "Having found that systemic IL-26 concentrations correlate negatively with both ACT scores and daily inhaled corticosteroid use, we also wondered whether there was a significant relationship between systemic IL-26 values and asthma exacerbations." (PMID 38622712, 2024). "Notably, IL-26 concentrations correlated with increasing Asthma Control Test (ACT) scores in a positive manner and with inhaled corticosteroid in a negative manner, amongst sensitized subjects with asthma." (PMID 38622712, 2024). "While elevations of these cytokines are not directly linked to the presence or absence of asthma, increasing systemic IL-26 concentrations are associated with multiple surrogate markers of improved asthma symptom control." (PMID 38622712, 2024). "Similarly, amongst children with asthma, IL-26 concentrations in induced sputum were enhanced in those with uncontrolled disease as compared to those with controlled disease." (PMID 38622712, 2024). "Despite a lack of correlation between systemic IL-26 and FEV1, we were interested in whether IL-26 levels might also correlate with other objective markers of asthma severity in a similar manner to the subjective correlation to ACT scores." (PMID 38622712, 2024). "Moreover, subjects with asthma requiring ≥ 1 course of oral corticosteroids in the preceding 12 months had decreased IL-26 concentrations." (PMID 38622712, 2024). "This was consistent with a study that found a positive correlation between IL-26 and IL-8 levels in cell-free bronchoalveolar lavage (BAL) fluid from patients with asthma, although these patients showed lower IL-26 concentrations in BAL fluid than did controls." (PMID 35463017, 2022). "Furthermore, local IL-26 concentrations are enhanced in uncontrolled compared with controlled disease among children with asthma." (PMID 31543817, 2019). "Although cytokines with strong proinflammatory potential such as TNF-α and IL-6 have meanwhile been implicated in at least several aspects of asthma pathogenesis, the effects of other TH17 cell derived factors such as IL-17F, IL-22, and IL-26 have only been investigated fragmentarily." (PMID 20976014, 2010). "As these observations were somewhat mixed and were discordant with the previous studies comparing local IL-26 and markers of asthma severity, we wondered whether systemic IL-26 concentrations may correlate with other surrogate markers of asthma severity in a manner similar to that of ACT scores." (PMID 38622712, 2024). "Serum concentrations of IL-26 and IL-17 A were measured and compared to subjective and objective demographic characteristics to test our hypothesis, namely that systemic IL-26 and IL-17 A levels are altered in allergen-sensitized children, particularly in those with asthma." (PMID 38622712, 2024). "However, systemic levels of IL-26 were significantly lower in subjects who had received at least one course of oral corticosteroids to treat an asthma exacerbation in the year preceding study participation as compared to those who had not taken oral corticosteroids." (PMID 38622712, 2024).
asthma (continued). "In this respect, the presence of elevated IL-26 and/or IL-17 A concentrations in our cohort was not distinctly associated with asthma or specific allergic disease, but rather emerge as general biomarkers of an inflammation that has traditionally been regarded as mediated by Type 2 cytokines." (PMID 38622712, 2024). "In “Neutrophils-Type” and “Interferon-Th1” (non-Th2) phenotype, interleukin-26 (IL26)-related function was upregulated and related to the severity of asthma." (PMID 34759961, 2021). "Similarly, lung fibroblasts release IL-26 in response to endotoxin via MAPK, NF-κB, and TRIF-dependent pathways, which are inhibited by asthma and COPD therapies such as hydrocortisone, salbutamol, and tiotropium." (PMID 41516201, 2025). "However, among adults with asthma, we found that bronchoalveolar lavage (BAL) IL-26 levels are clearly higher in those with uncontrolled asthma as compared to those with controlled disease." (PMID 38622712, 2024). "Our group has previously reported that IL-26 concentrations in BAL samples from adults with asthma are decreased compared to control subjects without asthma." (PMID 38622712, 2024). "Avramenko and colleagues observed that exhaled IL-26 concentrations are enhanced in both non-obese and obese asthmatics compared with control subjects without asthma." (PMID 38622712, 2024). "Conversely, other investigators found that systemic IL-26 levels are increased in adult patients with asthma as compared with non-asthmatic control subjects, regardless of disease severity or atopic status." (PMID 38622712, 2024). "In non-TH2 subtype (Neutrophils and Interferon-Th1) with severe asthma individuals, the neural signals and IL26-related co-expression module were dysregulated more significantly compared to that in non-severe asthma." (PMID 34759961, 2021). "Our study indicates that IL-26 is a potential biomarker of disease severity in pediatric asthma without signs of Th2-mediated inflammation." (PMID 27029915, 2016). "Additionally, other researchers reported that systemic IL-26 concentrations are elevated in adult asthma patients relative to non-asthmatic controls, independent of disease severity or atopic status." (PMID 41516201, 2025). "However, we were surprised to discover that systemic IL-26 and IL-17 A concentrations did not markedly differ between sensitized children with and without asthma." (PMID 38622712, 2024). "In this study, we determined whether systemic levels of the Type 17 cytokines IL-26 and IL-17 A are altered in dog allergen-sensitized children, with and without asthma, compared with non-sensitized children." (PMID 38622712, 2024). "As patients could not have evidence of an active asthma exacerbation at the time of enrolment, this difference was not due to direct inhibition of systemic IL-26 production by systemic glucocorticoids, a phenomenon which has been described in vitro." (PMID 38622712, 2024). "However, Salhi and colleagues did not observe a specific correlation between systemic IL-26 concentration and markers of disease severity in adults with asthma." (PMID 38622712, 2024). "Interestingly, serum levels of IL-26 in dog allergen-sensitized children without asthma were also elevated compared with non-sensitized children (p = 0.023)." (PMID 38622712, 2024). "However, the IL-26 concentrations did not markedly differ between allergen-sensitized subjects with and without asthma, eczema, allergic rhinitis, or a history of food allergy." (PMID 38622712, 2024). "Although we found that enhanced IL-26 concentrations are not restricted to children with asthma in our study material, we sought to determine whether IL-26 concentrations may correlate with disease severity amongst allergen-sensitized children with asthma." (PMID 38622712, 2024).
asthma (continued). "Along with this, we observed a statistically significant positive correlation between systemic IL-26 and IL-17 A concentrations, regardless of whether the analysis included all allergen-sensitized subjects or if it was restricted to only those with asthma." (PMID 38622712, 2024). "The GM13-up related to interleukin-26 (IL26, PIK3R5, and LRRC2) was much higher expressed in severe individuals while the GM12-down module related to the nervous system (10%, p = 1.77E-04, i.e., TUBB2B, SPOCK1, and ASCL1) was much lower expressed in severe asthma individuals." (PMID 34759961, 2021). "Thus, our current results introduce several strategies to modulate IL-26, with or without simultaneous activation of the innate arm of host defense, which are of potential utility in the treatment of diseases such as asthma and COPD." (PMID 31543817, 2019). "However, the contribution neither of IL-22 nor of IL-26 to asthma pathogenesis has been understood so far." (PMID 20976014, 2010). "Moreover, in a smaller case-control study, the same investigators demonstrated that IL-26 concentrations are elevated both locally in sputum as well as systemically in a cohort of adult women with severe uncontrolled asthma as compared with non-asthmatic control subjects." (PMID 38622712, 2024). "Moreover, they observed that obese subjects with asthma have enhanced systemic IL-26 concentrations as compared with control subjects, whereas non-obese subjects with asthma do not have clearly enhanced systemic IL-26 concentrations compared to control subjects without asthma." (PMID 38622712, 2024). "Moreover, patients that received one or more course of oral corticosteroids for asthma exacerbations in the year preceding study enrolment had significantly lower systemic IL-26 levels compared to the patients with asthma who had not received oral corticosteroids." (PMID 38622712, 2024).
inflammatory bowel disease (13 papers, 2012 to 2025). A spectrum of small and large bowel inflammatory diseases of unknown etiology. "Furthermore, levels of IL-19, IL-20, IL-24 and IL-26 are also elevated in serum of patients with inflammatory bowel disease, which is associated with the intergenic 6q23 variants tagged by rs6920220." (PMID 27799070, 2016). "A role of IL-26 in local inflammation has also been suspected in a genome-wide association studies showing that SNP within the il-26 gene region are susceptibility loci for inflammatory bowel disease with a high prevalence of articular involvement (i.e., RA, spondyloarthritis)." (PMID 23055831, 2012). "Specifically, IL-26-producing pro-inflammatory Th17 cells are found in chronically inflamed tissues such as chronic hepatitis C and inflammatory bowel diseases (IBD)." (PMID 39156888, 2024). "IL-26 is associated with the activation of Th17 and CD4+ IL-22+ T-cells; it also plays a role in inflammatory bowel disease, which may associate with the extra-pulmonary gastroenteritis manifestation during SMPP." (PMID 36618370, 2022). "A variety of studies have shown that IL-26 could enhance inflammatory response in RA, inflammatory bowel disease (IBD), or HCV infection." (PMID 31464651, 2019). "Thus, IL-26 stimulated monocytes are reported to promote Th-17 cell generation from non-Th17-committed memory T-cells in RA, However, IL-26 is also produced by Th17 cells in colonic lesions of patients with active inflammatory bowel disease (IBD)." (PMID 30319661, 2018). "The IL-20 cytokines IL-19, IL-20, IL-22, IL-24, and IL-26 are elevated in autoimmune/inflammatory diseases, such as in the skin of patients with psoriasis, in synovial fibroblasts, and macrophages of patients with rheumatoid arthritis and in patients with inflammatory bowel disease." (PMID 29967613, 2018). "The seRNAs IFNG-r-49 regulates the expression of IL-26 and IL-22 in inflammatory bowel disease (IBD), but does not regulate the expression of IFNG." (PMID 36726725, 2023).